IL1B (interleukin 1 beta)
Diseases named in the same sentence as IL1B in open-access papers (continued):
Sharing a sentence is not in itself a finding about the gene and the disease.
depression (continued). "The Ban-Xia-Hou-Pu decoction plays an antidepressant role by inhibiting the activation of NLRP3 inflammasomes and the production of IL-1β in the liver, hypothalamus, hippocampus, or prefrontal cortex of CUMS-induced depression rats." (PMID 33790789, 2021). "Depression is also considered to be related to inflammation, and EA was found to decrease both IL-1β and TNF-α expression, which was also found to alleviate leptin resistance and relieve depression." (PMID 34281592, 2021). "Proinflammatory cytokines such as interleukin (IL)-1β, IL-8, and tumor necrosis factor-α (TNF-α) among patients with depression have been reported to be significantly upregulated." (PMID 35155523, 2021). "The KBD formula normalized UMCS-induced anhedonia and hopeless behaviors in mice by restoring expression of the depression-related genes BDNF, CREB, GR, SGK1, FKBP5, IL-1β, IL-6, and TNF-α in the frontal cortex and hippocampus brain regions." (PMID 34358084, 2021). "Interleukins such as IL-1β, IL-6, and TNF-α become elevated in the brain during chronic stress and depression." (PMID 34078872, 2021). "Several studies have further found that the hippocampal concentrations of the pro-inflammatory cytokines IL-6, IL-1β, and TNF-α are elevated in mice with depression-like behavior." (PMID 34220460, 2021). "Expression of the microglial marker IBA-1 and inflammatory cytokines (IL1β, TNFα, BDNF) are up-regulated in the brain of patients with major depression and in animal models of depressive-like behavior." (PMID 34236532, 2021). "Inhibiting the expression of P2Y12 in the mPFC alleviated visceral pain and depression in IBD mice, weakened the activation of microglia, and reduced the expression of IL-1β in the mPFC." (PMID 34930362, 2021). "Reduce the expression of cytokines IL-1β, IL-6, TNF-α, and improve depression-like behavior in CUMS rats." (PMID 35185541, 2021). "The inflammatory etiology of fatigue and depression in MS was supported by evidence of increased serum and CSF concentration of inflammatory mediators such as TNF, interleukins (IL-1a, IL-1b, IL-6), IFNγ, and neopterin." (PMID 35242093, 2021). "Clinical studies have reported that the severity of depression in patients with PSD is positively correlated with the levels of IL-6, TNF-α, and IL-1β." (PMID 34725556, 2021). "In stress-induced animal models of depression, BDNF was shown to be markedly reduced by IL-1β and TNF-α and their downstream signaling pathways including NF-κB." (PMID 31019266, 2020). "Pain and depression, alongside liver expression of IDO-1/IL-1β mRNAs, were found to have subsided following an i.t. administration of an IL-1RA." (PMID 32842609, 2020). "In this sense, the main general markers of the cooccurrence of chronic pain and depression are related to central inflammation, particularly TNF-α, IL-1β, and IL-6." (PMID 32849076, 2020). "Proinflammatory cytokines, including IL-1β, IL-6, and TNF-α, are elevated in experimental and clinical studies of depression." (PMID 32410849, 2020). "Compared with wild-type mice, NLRP3 gene knockout mice didn’t exhibit depression-like behaviors in SPT or TST after 4 weeks of CUMS exposure; meanwhile, NLRP3 gene knockout prevented the promotion of IL-1β in serum and hippocampi of CUMS mice." (PMID 33132912, 2020). "Clinical studies also show that pro-inflammatory cytokines, e.g. TNF-α, IL-1β, IL-6, CCL-2, and IL-18, increase in patients with depression or anxiety." (PMID 32010477, 2020). "Previous studies found that pro-inflammatory cytokines, including tumor necrosis factor-α (TNF-α) and interleukin (IL)-6, IL-1β, and C-reactive protein (CRP), are markedly increased in the blood and CSF of patients with depression." (PMID 32922295, 2020). "The main general markers of the cooccurrence of chronic pain and depression were related to central inflammation, particularly, tumor necrosis factor (TNF)-α, interleukin (IL)-1β, and IL-6, as well as peripheral discrepancies in cortisol levels." (PMID 32849076, 2020).
depression (continued). "Postmortem analysis of the PFC of suicide victims has shown elevated levels of inflammatory cytokines such as IL‐1β, IL‐6, and TNF‐α 40, and suicide victims that have suffered from depression and schizophrenia exhibit increased microglial reactivity." (PMID 32125791, 2020). "High levels of neuro-inflammatory cytokines such as interleukin (IL)-1β, tumor necrosis factor-α (TNF-α), and IL-6 have been identified in patients with depression." (PMID 32922291, 2020). "A few postmortem brain studies suggest that expression of innate immune responders (IL-1β, IL-6, TNF-α) and TLRs are altered in postmortem brain of suicide victims, which includes suicide subjects with major depression." (PMID 30214045, 2019). "This review outlines the immunological mechanism of T1D and depression, with a particular emphasis on the role of tumor necrosis factor-α (TNF-α), IL-1β, and interferon-γ (IFN-γ) cytokines and their signaling pathways." (PMID 31049023, 2019). "Higher levels of interleukin (IL)-1β, IL-6, tumor necrosis factor (TNF)-α, and C-Reactive Protein (CRP) were reported in patients with depression by many investigators." (PMID 31252530, 2019). "To probe the potential mechanism of the occurrence of depression, we also detect the expression of ABL1, NF-κB1, STAT3, IL-6, IL-1β, and COX2 in the hippocampus of depressive mice." (PMID 31396300, 2019). "In our study, the levels of IL-1β, IL-6, and TNF-α were substantially increased in the hippocampus of the depression mice model induced by CUMS." (PMID 31068207, 2019). "A number of studies have indicated that various cytokines, such as IL-1β, IL-2, IL-6, TNF-α, and IFN-γ in serum or plasma of patients with depression were significantly increased." (PMID 31231295, 2019). "A meta-analysis found that IL-1β, IL-6, TNF and C-reactive protein (CRP) in peripheral blood are the most reliable biomarkers of inflammation in patients with depression." (PMID 31849598, 2019). "Subsets of patients who suffer from depression have elevations in circulating pro-inflammatory cytokines TNF-α, IL-1β, and IL-647." (PMID 30770787, 2019). "Since IL-1β and PGE2 increase in serum of stressed patients and potentially trigger depression, we used an animal model of chronic unpredictable stress (CUS) to investigate the potential impact of LTB4 over depression-like symptoms." (PMID 31057373, 2019). "Excessive secretion of proinflammatory cytokines such as IL-1β, IL-6, and TNF-α triggers depression-like behavior; indeed, increased levels of such cytokines are found in the periphery and brains of patients with major depressive disorders." (PMID 31241715, 2019). "Microglia release pro-inflammation mediators, such as IL-6, IL-1β, TNF-a, and nitric oxide that are considered links between chronic pain and depression." (PMID 30356873, 2018). "Proinflammatory cytokines like IL-1β, IL-6, TNF-α and IFN-γ are markers involved in the pathophysiology of depression." (PMID 29569964, 2018). "Inflammatory cytokines, such as interleukin (IL)-6, IL-1β, IL-8, and tumor necrosis factor (TNF)-α as well as the transcription factor NF-κB, function in the pathogenesis and development of chronic pain and depression." (PMID 30356873, 2018). "There is evidence that IL-1β-related inflammation in CNS mediated by NLPR3 inflammasome and P2X7 is strongly related to depression." (PMID 30662368, 2018). "As IL-1β, IFN-α/γ, TNF-α, and IL-6 have also been related to the onset and development of depression." (PMID 30662368, 2018). "We found linear correlations between IL-1β, TNF-α, and IL-8, and the severity of depression, as well as between IL-8 and anxiety level in patients with comorbid anxiety disorder (p < 0.05)." (PMID 29856741, 2018). "Higher levels of IL-1β, IL-6, and TNF-α in the brain were believed to induce depression due to DAMPs under stress." (PMID 29765402, 2018).
depression (continued). "Another important issue to emphasize is the synergistic effect that IL-1β exerts upon IFN-α-induced IDO upregulation, an event related to depression development." (PMID 30662368, 2018). "The alteration of IL-1β level, as well as that of BDNF, has been observed in major depressive patients, according to systematic Review and Meta-Analysis." (PMID 30042304, 2018). "The UPR acts on proinflammatory cytokines such as IL-8, IL-1β, and TNF-α, and these cytokines have been found to be upregulated in patients with major depression." (PMID 30186550, 2018). "We found linear correlations between IL-1β, TNF-α, and IL-8, and the severity of depression, as well as between IL-8 and anxiety level in patients with comorbid anxiety disorder." (PMID 29856741, 2018). "There is evidence to suggest that pro-inflammatory cytokines, including IL-1β, IL-6 and TNF-α, contribute to the onset and progression of depressive disorders." (PMID 29364170, 2018). "Convergent evidence of higher peripheral IL-1β, IL-6, TNF-α and CRP levels would support the psychoneuroimmunology theory as contributory to depressive syndromes and Alzheimer’s disease in elderly." (PMID 30104698, 2018). "Its relationship within the depressed group to whole blood mRNA expression of IL-1β is indicative of a link between HPA and immune dysregulation in depression." (PMID 29064428, 2017). "The relationship between microglial polarization and IL-1β secretion in neuroinflammation after a TBI, in AD, and in psychiatric disorders, such as major depressive disorder, bipolar disorder, autism and schizophrenia, has been well described." (PMID 29273062, 2017). "The findings of the present study demonstrate that BHB treatment exerts antidepressant-like effects in a CUS-induced rat model of depression, and that BHB attenuates stress-induced increases in hippocampal levels of IL-1β." (PMID 28794421, 2017). "Pro-inflammatory cytokines such as IL-1β, IL-6, TNF-α, NF-κB, and iNOS have been demonstrated to induce abnormal behaviors, such as decreased locomotor activity, exploration, and depression, which was confirmed in our experiment." (PMID 27120616, 2016). "It is thus unlikely that short-lived increases in cytokines playing a role in sickness behavior (such as IL-1β, IL-6, and TNF-α) will induce depression." (PMID 27504457, 2016). "We confirmed that the M1 markers (IL-1β, IL-6, TNFα, iNOS, and CCL2) were induced and that the M2 molecules (Ym1, Arg1, IL-4, IL-10, and TGFβ) were impaired in depression." (PMID 27716270, 2016). "The lack of a robust association between IL-1β and major depression might be partly attributable to measurement issues, as the concentrations of IL-1β are very low in blood and therefore more difficult to determine accurately using conventional immunological assays." (PMID 26065825, 2015). "In our experiments, the antidepressant-like effects of VAL and IMI were accompanied by a decrease in the expression of IL-1β and TNF-α in mice cortex, which is a cerebral area related to the pathophysiology of depression." (PMID 26170871, 2015). "For instance, numerous studies have reported that pro-inflammatory cytokines, most notably interleukin-1-beta (IL-1β), IL-6, interferon-alpha (IFN-α), and tumor necrosis factor-alpha (TNF-α), are altered in major depression and stressor-based animal models." (PMID 25477784, 2014). "Depression and anxiety were analyzed using the Hospital Anxiety and Depression Scale (HADS), and serum levels of IL-1β, IL-6, IL-8, IL-10, IL-12, TNF-α, and TGF-β were measured by Cytometric Bead Array." (PMID 25309921, 2014). "Proinflammatory cytokines, such as IL-1β, IL-6, and TNF-α, also elicit adverse behavioral effects (fatigue, soporific effects) and symptoms of anxiety and depression." (PMID 24348675, 2013). "Experimental and clinical evidence has suggested that depression and depressive symptoms are accompanied by elevated levels of pro-inflammatory cytokines, including IL6, TNFα and IL1β." (PMID 23876747, 2013).
depression (continued). "SNPs in the IL1B gene were shown to have effects on the responsiveness of the amygdala and ACC to emotional stimulation in major depression." (PMID 23199001, 2012). "In our model, MGO not only elevated depression-related markers such as GR and cortisol but also increased free MGO and pro-inflammatory cytokines (IL-1β, IL-6, TNF-α), implicating activation of inflammatory pathways that underlie psychoneuroimmunity-related depression." (PMID 41355970, 2026). "The mRNA expression levels of NLRP3, CASP1, and IL1B were higher in liver biopsies from AIH patients with depression than in those without depression." (PMID 41503678, 2026). "At baseline, depression was significantly correlated with TNF-α, IL-6, and IL-1β." (PMID 41600880, 2026). "LLE improved CRS-induced anxiety- and depression-like behaviors, reduced microglial activation in the hippocampus, and suppressed TLR4/MyD88/NF-κB signaling and downstream cytokine release (TNF-α, IL-6, IL-1β)." (PMID 42255668, 2026). "Moreover, MGO administration increased the levels of cytokines (IL-1β, IL-6, and TNF-α) in the serum, which led to neuropsychiatric disorders and depression as shown in behavior tests (i.e., OFT, TST, and FST)." (PMID 41355970, 2026). "Multiple studies have shown elevated levels of pro-inflammatory cytokines such as interleukin (IL)-1β, IL-6, tumor necrosis factor-α (TNF-α), and C-reactive protein (CRP) in patients with depression, particularly in those with treatment-resistant depression." (PMID 41303496, 2025). "IL-1β level in human CSF also showed inconsistent result with a meta-analysis describing one study with increased IL-1β in depression group while two studies showed no change in IL-1β level." (PMID 40179065, 2025). "Similar to pro-inflammatory factors such as IL-1β and MCP-1, MIP-1α and MIP-3α are key chemokines involved in immune cell recruitment and the propagation of inflammation, playing crucial roles in neuroinflammation and depression." (PMID 40453075, 2025). "Moreover, several pro-inflammatory cytokines that play an essential role in depression, such as TNF-α, IL-1β, and IL-6, are suppressed by ghrelin." (PMID 41375608, 2025). "Second, this study focused exclusively on IL-1β, IL-6, and TNF-α as inflammatory biomarkers associated with depression and did not examine the effectiveness of MBTs on other inflammatory markers." (PMID 41194929, 2025). "Elevated IL-1β levels in the hippocampus correlate with impaired long-term potentiation (LTP), weakened neurogenesis, and memory consolidation disorders, corresponding to clinical symptoms of depression, cognitive deficits in PTSD, and Alzheimer’s disease." (PMID 41008651, 2025). "In depression, pro-inflammatory cytokines such as IL-1β, IL-6 and TNF-α play a distinct role, not merely facilitating immune responses but also participating in the regulation of neurochemical, neuroendocrine and neuroplasticity processes." (PMID 40612748, 2025). "Mitochondrial transplantation may, therefore, exert its therapeutic effects on CRS-induced depression by restoring mitochondrial function and suppressing the NLRP3/caspase 1/IL1β signaling pathway." (PMID 40001487, 2025). "In addition, the oxidative stress that accompanies pain and depression activates glial cells, which release proinflammatory cytokines (TNF-α and IL-1β), chemokines, and neurotoxic substances such as NO in the central nervous system (CNS)." (PMID 40225229, 2025). "In the depression group, increase of IL-6 and IL-10, and decrease of IL-1β were observed compared to controls, with no changes detected for the other cytokines and the endothelial markers." (PMID 40179065, 2025). "The anti-inflammatory effects of AGOM could be related to its ability to modulate anxiety and depression and reduce oxidative stress, which in turn can affect the expression of COX-2 and IL-1β." (PMID 40076566, 2025).
depression (continued). "Another probiotic mixture containing L. lactis, L. cremoris, L. diacetylactis, L. acidophilus, and lactic yeasts also confers protection against LPS-induced depression and anxiety in CD1 mice by reducing the serum levels of IL-12, TNF-α, IL-1β, and TNF-α in the brain." (PMID 40804450, 2025). "The other cytokines measured—IL-1β, IL-4, IL-10, and TNF-α—showed little variation throughout the different phases, indicating their minimal involvement in the mediation of depression." (PMID 40564108, 2025). "MiR-532-5p alleviates depression-like behaviors in CUMS-exposed mice by suppressing the expression of IL-6, interleukin-1 beta (IL-1β), TNF-α, and monocyte chemoattractant protein-1 through inhibition of the signal transducer and activator of transcription 3 pathway." (PMID 40949123, 2025). "Inhibiting the high levels of IL-1β, IL-18, and TNF-α in the hippocampus, mangiferin exerts anti-inflammatory and neuroprotective properties, which may help reduce depression symptoms." (PMID 40696232, 2025). "However, the majority of existing epidemiological studies have primarily examined relationships between interleukin-1b (IL-1b), interleukin-2 (IL-2), interleukin-6 (IL-6), tumor necrosis factor-alpha (TNF-a), and other inflammatory factors and depression." (PMID 40530060, 2025). "In a diabetic neuropathy model with comorbid depression, DHM alleviated both neuralgia and depressive symptoms by suppressing P2X7 receptor expression, thereby reducing ERK1/2 phosphorylation and proinflammatory cytokines (TNF-α, IL-1β)." (PMID 40740995, 2025). "Similarly, increased concentrations of IL-1β, IL-6, and TNF-α have been reported in older adults with depression and across different depressive subtypes." (PMID 41333345, 2025). "Canonical pro-inflammatory cytokines, such as CRP, IL-1β, IL-6, and TNF-α, influence the central nervous system (CNS) function and contribute to changes in mood, social behavior, emotion regulation, and the onset and prognosis of depressive disorders." (PMID 41333345, 2025). "Interestingly, these inflammatory mediators are different from the ones previously reported in depression (TNF-α, IL-1β and IL-6)." (PMID 38473935, 2024). "It appears that increased production of IL‐1β and NLRP3 in the hippocampus may be effective in the development of increased depression‐like behaviors after ovariectomy." (PMID 39443283, 2024). "These analyses also show that a significant number of cytokines (including IL1α, IL1β, TNFα, IL2, IL12, IL18) and receptors (sIL-1RA, sIL-6R) are abnormally high in patients suffering from depression and that these disturbances are present in the acute and stability phases, in MDD and BD." (PMID 38499657, 2024). "Furthermore, the direct infusion of pro-inflammatory cytokines such as IL-1β and TNF-α into the brain has been shown to induce depression-like behaviors in rodents." (PMID 39130643, 2024). "In a model of LPS-induced depression, fluoxetine (20 mg/kg, i.g.)inhibited glial activation, decreasing levels of pro-inflammatory cytokines such as TNF-α, IL-1β, and IL-6, and increasing levels of the anti-inflammatory cytokine IL-10 in the hippocampus of male C57BL/6J mice." (PMID 38474387, 2024). "In prenatally stressed animals, increased levels of IL-1β and TNF-α might influence brain development and stress-related anxiety and depression-like behaviors." (PMID 39272253, 2024). "Furthermore, mangiferin downregulates the contents of IL-18, IL-1β, IL-6, and TNF-α in the hippocampus of the CUMS-induced depression mouse model by inhibiting the NLRP3/ASC/caspase-1 pathway." (PMID 38915473, 2024).